SHBG (sex hormone binding globulin)
Diseases named in the same sentence as SHBG in open-access papers (continued):
Sharing a sentence is not in itself a finding about the gene and the disease.
tumor (41 papers, 1990 to 2025). "In multiple tumour contexts, low SHBG states are associated with increased c-Myc and Bcl-2 expression and activity, upregulation of glycolytic effectors GLUT1, LDH and HK2, promoting mitochondrial resistance to apoptosis." (PMID 41586225, 2025). "At the end of study, using the regBase-CG database, we in silico assessed the potential role of the eight BC-involved polymorphisms of SHBG candidate genes as drivers of tumor development." (PMID 38396861, 2024). "Additionally, the association between SHBG expression levels and various classical tumor-related pathways was investigated." (PMID 38465341, 2024). "In the literature, a higher SHBG level has been associated with lower tumor [18F]-FES uptake." (PMID 34829366, 2021). "Reduced SHBG levels increase free testosterone and oestradiol, promoting tumour proliferation in hormone-responsive cancers, while elevated SHBG inhibits growth and metastasis even in receptor-negative phenotypes." (PMID 41586225, 2025). "We obtained the SHBG proteomic expression profile based on sample types, major subclass, and tumor histology by using the UALCAN-CPTAC dataset." (PMID 38465341, 2024). "In the cysts that lay centrally in the tumor, the concentration of SHBG tended to be higher than in those that lay eccentrically: 25 ± 14 vs. 16 ± 9 nmol/L (p = 0.059; n = 9 and 16, respectively)." (PMID 35659255, 2022). "Cyst fluid concentrations of growth hormone, testosterone, SHBG, and albumin correlated with tumor volume." (PMID 35659255, 2022). "Insulin also inhibits sex hormone-binding globulin levels, leading to higher levels of biologically active estrogens, which in turn can induce tumor cell proliferation and inhibit apoptosis." (PMID 36040641, 2022). "Consistent with this, reanalysis of the TCGA PRAD cohort (n = 497) showed that tumor T-stage progression was associated with SRD5A1 and HSD17B3 gene amplification and gain, but shallow or deep deletion of SHBG and HSD17B2 genes." (PMID 34298692, 2021). "When individual tumor burden was estimated and calculated for each liver, SHBG livers had significantly reduced tumor size compared with WT livers." (PMID 34830439, 2021). "SHBG livers had lower tumor numbers compared with WT livers, although the difference was not significant, likely because of the small number of mice used for the experiment." (PMID 34830439, 2021). "Excessive FM stimulates the aromatase activity while inhibiting the secretion of sex hormone-binding globulin, which increases the concentration of free estradiol, demonstrating pro-tumor effects." (PMID 34684550, 2021). "It lowers bioavailable estrogens through increased SHBG, improves insulin sensitivity, decreases pro-inflammatory cytokines, and enhances antioxidant defenses, collectively creating a less favorable environment for tumor development and progression." (PMID 40731797, 2025). "In addition, in the results based on tumor histology, SHBG protein expression was significantly lower in infiltrating ductal carcinoma, infiltrating lobular carcinoma, and mixed histology (all p < 0.05)." (PMID 38465341, 2024). "Similarly, after their culture with ECs, IL30-overexpressing PCs showed a dramatic upregulation of a wide range of oncogenes, which included CCND2, EGR3, IGFBP5, KLK3, PDLIM4, PTGS1 and SHBG and a few tumor suppressors, such as GPX3, FOXO1, MAX and NKX3-1." (PMID 38087324, 2023). "The inverse correlation was stronger (ρ = -0.44; p < 0.01) when the combined expression levels of IL12B and SHBG were considered, suggesting that inhibition of apoptosis may be a further downstream mechanism that mediates the tumor promoting activity of IL30." (PMID 38087324, 2023). "Particularly, SHBG EE2 tumor showed a larger area of aggregated nuclei than other tumors." (PMID 34830439, 2021).
tumor (continued). "SHBG's up-regulation in this group of patients may reflect improvement of liver function in response to reduction in tumor mass." (PMID 31355141, 2019). "Lower SHBG levels will result in increased levels of circulating unbound estrogen that may promote tumor progression." (PMID 29254480, 2017). "Comparison of clinical and pathologic characteristics by tumor SHBG intensity." (PMID 24386165, 2013). "Other organs known to produce SHBG include brain, uterus, testis, prostate, breast and ovary, and the local expressed SHBG may play an important role in tumor development." (PMID 24386165, 2013). "Lower levels of SHBG also result in increased levels of circulating unbound androgens which may result in tumor progression by themselves and further conversion to estrogens by adipose tissue and associated tumor effects." (PMID 23050155, 2012). "By raising SHBG, improving leptin sensitivity, and decreasing excess insulin-mediated signalling, nutritional and therapeutic ketosis may attenuate this endocrine, paracrine and autocrine growth axis and re-sensitise tumour cells to apoptotic initiation." (PMID 41586225, 2025). "Also, increased levels of bioavailable oestrogens in early adulthood (associated with insulin levels and decreased sex hormone binding globulin) could induce earlier differentiation of mammary cells and expression of the BRCA1 tumour suppressor gene." (PMID 34072619, 2021). "In addition to the positive tumor cells, endothelial cells were also immunoreactive for SHBG." (PMID 24386165, 2013). "Moreover, they may exert effects via oestrogen receptor-independent mechanisms, such as inhibition of tumour growth and angiogenesis, as well as stimulation of apoptosis and of sex hormone-binding globulin production (SHBG)." (PMID 21915130, 2011). "It has been convincingly shown that the increased content of circulating SHBG has a protective value for the development of the disease; however, these relationships (their presence and orientation) may depend on the pre/postmenopausal status of women and the molecular subtype of the tumor." (PMID 38396861, 2024). "Although tumor foci were similar in WT EE2 livers and WT livers, they were substantially larger in SHBG EE2 livers than in SHBG livers." (PMID 34830439, 2021). "Tumor incidence was 75% in SHBG livers, but WT, WT EE2, and SHBG EE2 livers exhibited 100% carcinogenesis." (PMID 34830439, 2021). "In the context of the selected analyzed diseases, we revealed a positive correlation between MOTS-c protein expression and SHBG levels and negative correlations with tumor size and patient height in ACC patients." (PMID 39201408, 2024). "Although WT EE2 livers did not exhibit an increased tumor burden compared to WT livers, SHBG EE2 livers had larger tumors than SHBG livers had." (PMID 34830439, 2021). "Liver weight and liver per body weight were both significantly increased in SHBG EE2 mice compared with WT EE2 mice, which may be induced by tumor weight." (PMID 34830439, 2021). "Additionally, a set of genes, including AFM, DYNLRB2, FDX1, and SHBG, were significantly downregulated in HCC-R tumor tissues with fold changes ≥4 involved in various small molecule biochemistry and molecular transport mechanisms." (PMID 24377043, 2013).
endocrine disorders (9 papers, 2018 to 2026). "Findings have important implications in the understanding of biological processes of SHBG and testosterone, with the potential for future work to determine the molecular mechanisms that underpin these associations that may be involved in endocrine disease processes." (PMID 30547757, 2018). "Real-world applications of SHBG measurement may include risk stratification and early identification of youth at risk for CVD and additional criteria for the diagnosis of endocrine disorders such as PCOS." (PMID 40863113, 2025).
heart disease (4 papers, 2019 to 2025). "We also saw the association of sex hormone–binding globulin (SHBG), and free androgen index (FAI) (calculated by the ratio of total testosterone level to SHBG) with heart disease was different between women and men, and between pre- and post-menopausal women." (PMID 37730580, 2023). "As a final example, a sex-specific MR studied the effect of genetically predicted sex hormone binding globulin (SHBG) on ischaemic heart disease, using a sex-specific SNP-selection." (PMID 37024639, 2023).
infection (4 papers, 2021 to 2024). The state of being infected such as from the introduction of a foreign agent such as serum, vaccine, antigenic substance or organism. "Understanding the impact of the infection also on serum PRL, E2, and SHBG levels would be useful to have a more complete picture of the pathogenetic mechanisms through which the infection causes testicular dysfunction." (PMID 38345682, 2024). "The increase in TT as the duration of infection progresses is actually misleading and depends mainly on SHBG elevation typical of these patients." (PMID 33289905, 2021). "Full model included as independent variables age, BMI, years of infection, cART duration, spine BMD, CD4 + nadir count, TT, SHBG, cFT, LH and FSH." (PMID 34460073, 2022). "In fact, there was a strong positive correlation between TT levels and SHBG, and even more importantly between SHBG and HIV infection duration, which may explain both the apparent increase of TT with infection history, and the relative stability of the cFT." (PMID 33289905, 2021).
inflammation (3 papers, 2016 to 2022). Aberrant reaction of the microcirculation characterized by movement of fluid and leukocytes from the blood into extravascular tissues. "Other features include uneven gonadotropin secretion, i.e., increased luteinizing hormone (LH), increased LH:FSH (follicle-stimulating hormone) ratio, low sex hormone-binding globulin (SHBG), and chronic inflammation." (PMID 36231000, 2022).
liver (3 papers, 2016 to 2022). "SHBG is produced in the liver, and SHBG levels are affected by diseases of the liver through a variety of mechanisms." (PMID 26761949, 2016).
renal disease (3 papers, 2012 to 2024). "Out of 800 men and postmenopausal women with T2DM solicited for participation, 25 declined, 36 lacked essential laboratory data or had severe cardiac, hepatic, renal disease or thyroid dysfunction, 74 were premenopausal women, and 114 possessed a variant SHBG SNP at rs6257 or rs6259." (PMID 39020340, 2024).
neurodegenerative disease (2 papers, 2025). A disorder of the central nervous system characterized by gradual and progressive loss of neural tissue and neurologic function. "The potential association between SHBG and neurodegenerative diseases has been investigated in several studies employing Mendelian randomization methods to explore the impact of genetically predicted sex hormone levels on disease risk." (PMID 40437610, 2025). "In general, there are few studies on SHBG and neurodegenerative diseases, and more studies are needed to explain the relationship between SHBG and neurodegenerative diseases." (PMID 40149599, 2025). "Evidence suggests that the plasma SHBG level may be an effective biomarker of neurodegenerative diseases." (PMID 40149599, 2025). "Consequently, the exact role of SHBG in neurodegenerative diseases and its clinical translational value require further validation through rigorously designed studies." (PMID 40437610, 2025).
gastrointestinal disorders (1 paper, 2025). "Some studies have demonstrated that SHBG-bound testosterone is distributed differently in men and women A significant association between SHBG and testosterone in gastrointestinal disorders has been observed in various studies." (PMID 39944207, 2025).
gynecological diseases (1 paper, 2023). "Therefore, we analyzed the effects of DHEAS and SHBG levels on gynecological diseases." (PMID 38075074, 2023).
psychiatric disorder (1 paper, 2025). A disorder characterized by behavioral and/or psychological abnormalities, often accompanied by physical symptoms. "This pattern observed in our study suggestively indicates a shared genetic architecture among SHBG, testosterone, and estradiol and psychiatric disorders, thereby helping us better understand the relevance of common variants that influence all three of these sex hormones in psychiatric disorders." (PMID 40727568, 2025). "Previous observational and causal inference studies have suggested a potential involvement of SHBG in various psychiatric disorders." (PMID 40727568, 2025). "In conclusion, our study reveals genetic correlations between levels of endocrine hormones, particular sex hormones such as SHBG, and multiple psychiatric disorders, thereby highlighting a shared genetic architecture driven by common variants." (PMID 40727568, 2025). "Interestingly, for each Bonferroni-significant genetic correlation we observed between SHBG and the evaluated psychiatric disorders, either testosterone, estradiol, or both also showed suggestive, nominally significant genetic correlations in the same direction." (PMID 40727568, 2025).
reproductive system disorder (1 paper, 2025). A disease involving the reproductive system. "SHBG, a liver-produced protein that regulates sex hormones is associated with metabolic and reproductive system disorders." (PMID 41071435, 2025).
SHBG also shares sentences with these, for which no sentence is quoted: Anxiety (13 papers); ovarian dysfunction (6); alopecia (5); adenocarcinoma (3); gallstones (3); hypercortisolism (3); liver cirrhosis (3); melanoma (3); Menstrual disorder (3); Ovarian cyst (3); Thromboembolism (3); bipolar disorder (2); bladder cancer (2); cutaneous melanoma (2); ductal carcinoma in situ (2); endothelial dysfunction (2); epilepsy (2); Hepatitis B (2); hyperthyroxinemia (2); insomnia (2); intrauterine growth restriction (2); Klinefelter syndrome (2); psoriasis (2); abnormal glucose tolerance (1); Addison’s disease (1); age (1); alcohol (1); alcohol addiction (1); allergic rhinitis (1); allergies (1).
A further 98 diseases each share a sentence with SHBG in 1 paper.